INS (insulin)
Diseases named in the same sentence as INS in open-access papers (continued):
Sharing a sentence is not in itself a finding about the gene and the disease.
Insulin resistance (continued). "Type 2 diabetes is a metabolic disease that causes chronic hyperglycemia due to decreased insulin action caused by decreased endogenous insulin secretory capacity of pancreatic β-cells and decreased insulin sensitivity (insulin resistance)." (PMID 35574023, 2022). "The increased cortisol levels under circadian disruption also contribute to insulin resistance, as well as deficiency in insulin secretion, as referred to in Section 3.3." (PMID 35008933, 2022). "This has direct implications on insulin sensitivity since central fat deposits are consistently associated with increased insulin resistance and associated with more inflammation as compared to deposits in peripheral muscles." (PMID 35391836, 2022). "But the treatment of hyperthyroidism both in this study and in previous studies was observed to be associated with a decrease in glucose, insulin, and insulin resistance as measured by HOMA-IR." (PMID 35929907, 2022). "There are very rare cases of mutations in the IR gene which can lead to insulin resistance, requiring 100-fold or more insulin than that required by a typical diabetic patient." (PMID 35884888, 2022). "In type 1 diabetes, these disruptions are caused by hypoinsulinemia, but in type 2 diabetes, they are caused by insulin resistance and decreased insulin secretion." (PMID 35802659, 2022). "These stresses induce adipocyte insulin resistance and several studies have shown that a disruption of insulin signaling in adipocytes causes whole body glucose intolerance and systemic insulin resistance." (PMID 36010657, 2022). "Insulin resistance is known to contribute to the development of cognitive dysfunction due to, at least in part, the loss of the neuroprotective effects attributed to insulin." (PMID 35615716, 2022). "This includes, for instance, heart failure, dementia and other diseases that are linked to the activity of the hormone insulin becoming modified throughout the body, a defect called insulin resistance." (PMID 35037854, 2022). "This causes a reduction in insulin clearance as a compensatory mechanism to insulin resistance in obesity." (PMID 36009446, 2022). "Type 2 diabetes (T2DM) is a chronic metabolic disease with abnormally high blood glucose caused by insufficient insulin secretion or insulin resistance." (PMID 35094288, 2022). "Associations of valine with insulin resistance (insulin and HOMA-IR) were lost in BAT-positive participants in both hyperthyroid and euthyroid state." (PMID 35256693, 2022). "Type 2 diabetes is associated with insulin resistance, impaired insulin secretion and liver steatosis." (PMID 35145074, 2022). "This is caused by low insulin levels as well as increased insulin resistance in hepatocytes in T2D patients." (PMID 34984701, 2022). "A pathophysiological mechanism in Asian T2DM is closely linked to low insulin secretion, β-cell mass, and inability to compensate for insulin resistance." (PMID 35956399, 2022). "Insulin resistance due to statins is caused by disturbances in the insulin signal transduction pathway." (PMID 35892446, 2022). "T2D is a metabolic disorder characterized by hyperglycemia caused by one or both of insulin resistance and insufficient insulin production." (PMID 35885938, 2022). "This review will summarize the research progress on the association and related underlying mechanisms of R4 RGS subfamily members in insulin secretion and insulin resistance and analyze their potential value in the treatment of T2DM." (PMID 36497154, 2022). "Insulin resistance results in downregulation of receptors of insulin, which causes the neurotropic effect of insulin on the brain to decrease." (PMID 36258952, 2022). "It is a hereditary condition caused as a result of insulin resistance, insufficient insulin secretion, or a combination of both, largely affecting an older population than Type 1 diabetes." (PMID 35807526, 2022).
Insulin resistance (continued). "The elevation of gluconeogenic gene expressions in the liver resulting from insulin secretion deficiency and/or insulin resistance leads to the abnormal increase in hepatic gluconeogenesis, which finally increases fasting blood glucose." (PMID 35800345, 2022). "Further, these diseases share a common pathology and pathogenic mechanisms that include insulin resistance, impaired insulin signalling, oxidative stress, inflammation and amyloid deposition." (PMID 36555450, 2022). "Improvements in glucose metabolism with dietary restriction and weight loss are known to arise from reduced insulin resistance but also enhanced beta-cell insulin secretion." (PMID 35662920, 2022). "Obesity is a major cause of impaired insulin signaling and, therefore, insulin resistance development." (PMID 35548566, 2022). "Reduced insulin action is associated with reduced insulin-stimulated activity of enzymes such as glycogen synthase and hexokinase, and adipose tissue insulin resistance (adipo-IR) plays important roles." (PMID 35320949, 2022). "Children exposed to IUGR have increased insulin resistance, and low birth weight has also been linked to altered insulin sensitivity." (PMID 36714657, 2022). "We have previously demonstrated that insulin resistance, as assessed by insulin sensitivity index and Matsuda index, was associated with PBR suggesting its detrimental effect on glycocalyx integrity." (PMID 35215285, 2022). "In contrast, β pancreatic cells in type 2 diabetes (T2D) become depleted over time due to compensatory insulin secretion caused by insulin resistance." (PMID 35055050, 2022). "Insulin resistance in skeletal muscle is caused by impaired insulin signaling and many post-receptor intracellular defects including impaired glucose transport, glucose phosphorylation, and reduced glucose oxidation and glycogen synthesis." (PMID 36230963, 2022). "Insulin resistance is associated with a reduced ability of insulin to activate a variety of events in the insulin signaling system, such as tyrosine phosphorylation of IRS-1." (PMID 35320949, 2022). "It has been suggested that hyperglycemia causes the progression of insulin resistance through the generation of reactive oxygen species (ROS), which abolish insulin-induced tyrosine autophosphorylation of the insulin receptor." (PMID 35455055, 2022). "Proinflammatory cytokines can cause insulin resistance in adipose, skeletal muscle, and liver tissue by inhibiting insulin signal transduction." (PMID 35320949, 2022). "Streptococcus was found positively associated with insulin, connecting peptide, and index of homeostatic model assessment of insulin resistance." (PMID 35399957, 2022). "Nevertheless, similar to the effects of polyphenols, the protective role of compounds such as carotenoids or vitamins E and C on insulin-targeted tissues and insulin resistance associated with periodontal disease still needs to be elucidated." (PMID 35327570, 2022). "Insulin resistance, defined as poor insulin sensitivity and deficient insulin signaling, is a well-known risk factor for DM." (PMID 35765060, 2022). "Lipotoxicity impairs insulin signaling in the kidney, liver, and skeletal muscle, causing insulin resistance." (PMID 36726470, 2022). "Insulin resistance and obesity are well known risk factors for type 2 diabetes and higher insulin levels and a high homeostatic model assessment index has been demonstrated in obese compared with nonobese adults with PWS." (PMID 35150573, 2022). "It is well known that the antilipolytic effect of insulin is less sensitive to insulin deficiency or insulin resistance than its effect on glucose metabolism." (PMID 35625574, 2022). "Dietary intake of flavonoids is associated with biomarkers of insulin resistance and systemic inflammation, such as fasting insulin levels, C-reactive protein, and interleukin (IL)-6." (PMID 36632095, 2022).
Insulin resistance (continued). "Similar to this, IL-β contributes to the progression of insulin resistance in the peripheral tissues by causing inflammation in those tissues as a result of those tissues’ diminished capacity to use insulin in response to glucose." (PMID 36678531, 2022). "Obesity is often associated with insulin resistance (IR), a condition characterized by a reduced response of the tissues to insulin-mediated actions." (PMID 36612926, 2022). "Alistipes are associated with the release of gut hormones that regulate insulin release and reverse insulin resistance." (PMID 36360018, 2022). "A diminution in metabolic response to insulin in the target cells, triggering a hinderance to decrease the high blood glucose levels by circulating insulin, causes insulin resistance." (PMID 36290804, 2022). "As well, sodium butyrate supplementation (5% w/w) to a high fat diet in mice attenuated obesity-associated insulin resistance by reducing fasting blood glucose and insulin levels and homeostasis model assessment-estimated insulin resistance (HOMA-IR)." (PMID 35889783, 2022). "Early studies suggested that in fructose-fed rats insulin resistance is caused by the reduced ability of insulin to inhibit neoglucogenesis in the liver, while glucose uptake by the skeletal muscle was apparently unchanged." (PMID 36289636, 2022). "Brain insulin resistance is generally established due to low insulin or/and IGF receptors levels, while deficiencies of insulin and IGF are associated with expression changes in the brain." (PMID 35101010, 2022). "The effects of dietary fats on insulin sensitivity have been examined in metabolic syndrome with underlying insulin resistance." (PMID 35807818, 2022). "Over 75% of type 2 diabetic patients also have hypertension due to the high insulin levels associated with insulin resistance increasing salt and water retention and the association of insulin resistance with increased sympathetic nervous system activity." (PMID 35967126, 2022). "They identified four variants associated with a clear insulin resistance pattern, two associated with reduced insulin secretion with normal fasting glycemia, and one with insulin processing." (PMID 35913467, 2022). "Hyperglycemia is associated with hyperinsulinemia, defined as increased insulin serum concentration and insulin resistance." (PMID 35757631, 2022). "Finding that the EDF dietary pattern was associated with higher adiposity, insulin, and insulin resistance only in girls deserves further discussion." (PMID 35276899, 2022). "Insulin resistance in PCOS is likely to be caused by a post-receptor defect in insulin signaling, with increased serine phosphorylation and decreased protein kinase activity." (PMID 36071485, 2022). "The resulting increase in circulating free fatty acids (FFAs) in turn worsens insulin resistance by causing alterations in the insulin signaling cascade in different organs, thus creating a vicious cycle." (PMID 35054972, 2022). "Insulin resistance increases the levels of insulin in the serum, which causes hepatocytes to promote hepatic lipid synthesis through several insulin-sensitive signaling factors and induces a vicious cycle of inflammation." (PMID 35198905, 2022). "In this sense, it has been reported that polysaccharides from algae with a low Mw value (4–20 kDa) have a lower GI because they promote insulin secretion, thus, protecting the pancreas and decreasing the risk of insulin resistance development." (PMID 36290380, 2022). "T2DM is a metabolic disorder characterized by chronic hyperglycemia and improper lipid, carbohydrate, and protein metabolism, caused by insulin resistance and inadequate insulin release." (PMID 35729499, 2022). "The perpetuation of inflammation experienced by patients with psoriasis gives rise to cytokines, adipokines and angiogenic factors that, generated in excess, are capable of acting as insulin antagonists, thus causing insulin resistance." (PMID 36145322, 2022).
Insulin resistance (continued). "Excessive energy intake can result in multiple metabolic diseases, including type 2 diabetes mellitus (T2DM), due to high-level blood glucose, deficient insulin secretion, and insulin resistance." (PMID 36699697, 2022). "Different reports have shown that a deficiency in macroautophagy induces insulin resistance in liver cells and impairs insulin secretion in the pancreas." (PMID 35326371, 2022). "Regular physical activity is beneficial not only in lowering insulin resistance and increasing insulin production but also in lowering the risk of cardiovascular disease and obesity in diabetic individuals." (PMID 35646765, 2022). "The fat level in the liver is closely related to insulin resistance, and deterioration of insulin resistance causes islet β cells to secrete excessive insulin." (PMID 35571083, 2022). "GD is typically associated with both chronic insulin resistance during pregnancy and β-cell dysfunction, indicating the underlying pathophysiology to be both insulin resistance from tissues and impaired β-cell function." (PMID 35055022, 2022). "M1-induced inflammation and subsequent upregulation of the TNF-α/JNK pathway disrupt insulin signaling, causing insulin resistance (IR) in diabetic adipose tissue." (PMID 36477360, 2022). "For example, abnormally higher levels of circulating insulin, due to insulin resistance in obesity, can cause DNA damage by increasing the translocation of Akt into mitochondria and its activation of NADPH oxidase." (PMID 36038791, 2022). "The results from different studies conducted suggested that activation of the same or related stress pathways causes insulin resistance and decreased insulin production." (PMID 35600869, 2022). "Type 2 diabetes patients had high LD accumulation in β cells, which was associated with insulin resistance, hyperglycemia, aging and β cell dysfunction involving decreased mature insulin granules." (PMID 36204103, 2022). "The negative regulation of the insulin signaling pathway by PTP1B helps the researchers to consider it as a potential therapeutic target for the treatment of insulin resistance and its associated complications." (PMID 36875821, 2022). "The T allele mutation at TCF7L2 rs7903146 loci has been linked with impaired insulin secretion and hepatic insulin resistance." (PMID 35685576, 2022). "The mechanistic basis for the causative role of adipokines in blunting insulin signaling and ensuing insulin resistance has been extensively reviewed." (PMID 36009446, 2022). "Insulin signaling pathway which is associated with insulin resistance, as well as altered hepatic glycolysis and glycogen synthase, branches to alter hepatic energy status." (PMID 36570152, 2022). "The cellular and molecular mechanisms underlying DCI were thought to be related to depleted insulin secretion, insulin resistance, hyperglycaemia, systemic inflammation, and neuroinflammation." (PMID 35899118, 2022). "Remarkably, methylation-altered genes in umbilical cord blood were associated with pathways insulin resistance and insulin secretion." (PMID 35606885, 2022). "This is surprising, as impaired glucose tolerance is often associated with a deficit in β-cell insulin secretion and peripheral insulin resistance." (PMID 35846351, 2022). "Type 2 diabetes (T2D) is a multi-factorial disease represented by insulin resistance, impaired insulin secretion and hyperglycemia with obesity as the most common cause of insulin resistance." (PMID 36686443, 2022). "The incidence of T2DM is associated with insulin resistance (IR) induced by decreased insulin sensitivity and insufficient insulin secretion induced by islet cell destruction and dysfunction." (PMID 35392498, 2022). "This study showed that overexpression of miR-155 in female and male mice improved glucose tolerance and insulin sensitivity, while conversely, miR-155 deficiency caused hyperglycemia, impaired glucose tolerance and insulin resistance." (PMID 36319747, 2022).
Insulin resistance (continued). "Insulin resistance, which is defined as loss of appropriate response to ordinary circulating insulin levels in insulin-targeted cells, such as hepatocytes, adipocytes, and skeletal muscle cells, is one of the pivotal causes of T2DM." (PMID 35571202, 2022). "Insulin resistance prevents insulin from performing its normal physiological function, causing high blood glucose." (PMID 36699072, 2022). "Insulin resistance is a hallmark of type 2 diabetes that early in the disease is compensated for by increased beta-cell insulin secretion." (PMID 35414066, 2022). "Insulin is known to have a dubious relationship with hypertension, as physiologically it promotes vasodilation; but with development of insulin resistance and impairment of associated PI3-kinase signalling, this vasodilatory effect is lost." (PMID 36085061, 2022). "LPS can permeate intestinal epithelial cells and bind to chylomicrons, which are subsequently transported to insulin sensitive organs, eventually causing inflammation and insulin resistance." (PMID 35057558, 2022). "Type 2 DM is caused by peripheral insulin resistance, where a normal or elevated insulin level produces an attenuated biological response and is followed by beta cell destruction which alters glucose homeostasis." (PMID 36556443, 2022). "HOMA-IR is often used in investigating and quantifying insulin resistance because of the simplicity of the underlying mathematical model (HOMA-IR = fasting glucose [mg] × fasting insulin [mu/L]/22.5)." (PMID 36432623, 2022). "In obesity and pregnancy, beta cell expansion is associated with enhanced insulin secretion, which compensates for insulin resistance." (PMID 34932133, 2022). "Evidence suggests that insulin levels and insulin resistance are associated with myocardial steatosis, cardiac remodeling, and fitness in women with obesity." (PMID 36568107, 2022). "Both PDIA3 and CALR were positively associated with insulin resistance, cholesterol, and triglycerides and the number of criteria identifying metabolic syndrome and negatively with fasting and post-challenge insulin sensitivity." (PMID 36213269, 2022). "In non-diabetic people, impaired fasting glucose, or obesity-related reduction of insulin sensitivity, as assessed by euglycemic hyperinsulinemic clamp and other markers of insulin resistance, are associated with increased epicardial fat." (PMID 35204677, 2022). "Diabetes type 2 is characterized by progressive loss of adequate β-cell insulin secretion and onset of insulin resistance with increased insulin demand, which contributes to the development of hyperglycemia." (PMID 35840638, 2022). "An epidemiological survey found that insulin resistance, hyperglycemia, and high insulin levels were risk factors for cancer." (PMID 35592685, 2022). "Several studies have reported significant associations of genetic variants with fasting glucose, fasting insulin, fasting proinsulin, and insulin resistance." (PMID 35956377, 2022). "Yet, from 4 to 10 years, we have observed sex differences that are consistent for both adiposity and some cardiometabolic risk factors (insulin and insulin resistance)." (PMID 35276899, 2022). "With regard to the association between SD and insulin resistance, several studies have demonstrated that SD has detrimental effects on insulin sensitivity and glucose tolerance, and causes increased insulin resistance, which is an indicator of prediabetes." (PMID 35270465, 2022). "Insulin resistance in originally insulin-sensitive hepatocytes causes marked alterations in glucose and lipid metabolism." (PMID 35436984, 2022). "Patients with T1DM and T2DM both manifested by hyperglycemia have different insulin level, that the former is mainly insulin-deficient and the latter is characterized by insulin resistance." (PMID 36120431, 2022). "Type 2 diabetes is caused by insulin resistance, which refers to impaired sensitivity to insulin-mediated glucose disposal or insufficient insulin secretion." (PMID 35629891, 2022).